PAGR1 (PAXIP1 associated glutamate rich protein 1)
Description:
Its association with the histone methyltransferase MLL2/MLL3 complex is suggesting a role in epigenetic transcriptional activation. However, in association with PAXIP1/PTIP is proposed to function at least in part independently of the MLL2/MLL3 complex. Proposed to be recruited by PAXIP1 to sites of DNA damage where the PAGR1:PAXIP1 complex is required for cell survival in response to DNA damage independently of the MLL2/MLL3 complex. However, its function in DNA damage has been questioned (By similarity). During immunoglobulin class switching in activated B-cells is involved in transcription regulation of downstream switch regions at the immunoglobulin heavy-chain (Igh) locus independently of the MLL2/MLL3 complex (By similarity). Involved in both estrogen receptor-regulated gene transcription and estrogen-stimulated G1/S cell-cycle transition. Acts as a transcriptional cofactor for nuclear hormone receptors. Inhibits the induction properties of several steroid receptors such as NR3C1, AR and PPARG; the mechanism of inhibition appears to be gene-dependent.
Synonyms: GAS; C16orf53; PA1; MGC4606
Tractability: PROTAC: its protein half-life has been measured.
Gene: Protein-coding gene on chromosome 16 (29,816,152 to 29,822,489, forward strand). Ensembl gene ENSG00000280789.
Subcellular location: Nucleus
Pathways (Reactome):
Gene expression (Transcription): Epigenetic regulation of gene expression by MLL3 and MLL4 complexes; Formation of WDR5-containing histone-modifying complexes; MLL4 and MLL3 complexes regulate expression of PPARG target genes in adipogenesis and hepatic steatosis
Developmental Biology: Activation of anterior HOX genes in hindbrain development during early embryogenesis
Gene Ontology:
Molecular function: nuclear estrogen receptor binding; protein binding
Biological process: positive regulation of cell cycle G1/S phase transition; positive regulation of intracellular estrogen receptor signaling pathway; positive regulation of transcription by RNA polymerase II
Cellular component: histone methyltransferase complex; MLL3/4 complex; nucleus; nucleoplasm
Genetic constraint (gnomAD): Loss-of-function variants: 20 observed, 18.02 expected, observed/expected ratio (o/e) 1.11, 90% interval 0.78 to 1.61. The upper end of that interval is the gene's LOEUF score, 1.61, which puts it in group 6 of 6, group 1 being the genes least tolerant of losing a copy. Missense variants: 338 observed, 322.19 expected, observed/expected ratio (o/e) 1.05, 90% interval 0.96 to 1.15. Synonymous variants: 161 observed, 136.27 expected, observed/expected ratio (o/e) 1.18, 90% interval 1.04 to 1.35.
Homologues: Orthologues: chimpanzee PAGR1 (99% identical), macaque PAGR1 (97% identical), pig PAGR1 (91% identical), dog PAGR1 (90% identical), rabbit PAGR1 (89% identical), guinea pig PAGR1 (88% identical), mouse Gm42742 (87% identical), mouse Pagr1a (87% identical), tropical clawed frog pagr1 (53% identical), zebrafish pagr1 (44% identical), Drosophila melanogaster Pa1 (14% identical).
Diseases named in the same sentence as PAGR1 in open-access papers:
PAGR1 is named in the same sentence as 38 diseases in open-access papers, as found by Europe PMC text mining. Sharing a sentence is not in itself a finding about the gene and the disease. The quoted sentences say what the papers report.
breast carcinoma (5 papers, 2013 to 2022). "The large majority (10/13) of these genes were reported to play a role in the regulation of estrogen and/or progesterone response in human breast cancer (NCOA7:; NCOA3:; USP22:; MED24:; CCAR1:; CRY2:; STAT5B:; PAGR1:; TAF1:; PHB2:)." (PMID 35996163, 2022).
Hepatic steatosis (1 paper, 2025). Steatosis is a term used to denote lipid accumulation within hepatocytes. "Importantly, muscle-specific deletion of PAGR1 protects against high-fat-diet-induced insulin resistance and hepatic steatosis." (PMID 40703063, 2025).
language disorder (1 paper, 2025). A category of disorders characterized by an impairment in the development of an individual's language capabilities, which is in contrast to his/her non-verbal intellect. "Proband 7, a male with borderline intellectual functioning, language disorder, and EEG abnormalities, exhibited a duplication in the 16p11.2 chromosomal region, which encompasses 30 genes, such as PRRT2, PAGR1, and TAOK2." (PMID 41009966, 2025).
genetic disease (1 paper, 2023). "Among protein-coding genes located between BP4 and 5, five genes, including TAOK2 (a pLI score of 1.00), CORO1A (0.97), MAZ (0.93), PAGR1 (0.74), and PRRT2 (0.59), have a pLI value of 0.5 or more and are associated with symptoms related to 16p11.2 deficits and are implicated in genetic disease." (PMID 38203422, 2023).
PAGR1 also shares sentences with these, for which no sentence is quoted: infection (7 papers); tumor (7); hepatocellular carcinoma (2); ovarian carcinoma (2); Azoospermia (1); bacterial disease (1); Cachexia (1); cancer (1); cardiomyopathies (1); co-infection (1); Cornelia de Lange syndrome (1); cyst (1); diffuse astrocytoma (1); endometrial cancer (1); Hyperglycemia (1); Insulin resistance (1); invasive breast carcinoma (1); Kabuki syndrome (1); Kleefstra syndrome (1); leukemia (1); lung carcinoma (1); lymph node metastasis (1); male infertility (1); melanoma (1); metabolic disease (1); migraine (1); neurodevelopmental disorder (1); pancreatic cancer (1); pneumonia (1); prostate carcinoma (1).
A further 4 diseases each share a sentence with PAGR1 in 1 paper.